RCAN1 (regulator of calcineurin 1)
Description:
Inhibits calcineurin-dependent transcriptional responses by binding to the catalytic domain of calcineurin A. Could play a role during central nervous system development (By similarity).
Synonyms: MCIP1; ADAPT78; CSP1; DSCR1
Tractability: PROTAC: ubiquitination databases record sites on it; its protein half-life has been measured.
Gene: Protein-coding gene on chromosome 21 (34,513,142 to 34,615,113, reverse strand). Ensembl gene ENSG00000159200.
Subcellular location (Human Protein Atlas): Cytosol
Gene Ontology:
Molecular function: protein binding; calcium-dependent protein serine/threonine phosphatase regulator activity; nucleic acid binding; protein phosphatase inhibitor activity
Biological process: negative regulation of calcineurin-NFAT signaling cascade; calcium-mediated signaling; negative regulation of smooth muscle cell differentiation; response to estrogen; response to mechanical stimulus; skeletal muscle tissue development
Cellular component: cytoplasm; nucleus
Genetic constraint (gnomAD): Loss-of-function variants: 11 observed, 20.15 expected, observed/expected ratio (o/e) 0.55, 90% interval 0.34 to 0.9. The upper end of that interval is the gene's LOEUF score, 0.9, which puts it in group 3 of 6, group 1 being the genes least tolerant of losing a copy. Missense variants: 291 observed, 290.97 expected, observed/expected ratio (o/e) 1, 90% interval 0.91 to 1.1. Synonymous variants: 136 observed, 120.17 expected, observed/expected ratio (o/e) 1.13, 90% interval 0.98 to 1.3.
Homologues: Orthologues: guinea pig RCAN1 (96% identical), pig RCAN1 (94% identical), dog RCAN1 (93% identical), chimpanzee RCAN1 (73% identical), macaque RCAN1 (70% identical), rat Rcan1 (69% identical), mouse Rcan1 (69% identical), rabbit RCAN1 (68% identical), tropical clawed frog rcan1 (68% identical), zebrafish rcan1a (48% identical), Drosophila melanogaster sra (35% identical), Caenorhabditis elegans rcan-1 (30% identical). Paralogues in human: RCAN2 (50% identical), RCAN3 (48% identical).
Diseases named in the same sentence as RCAN1 in open-access papers:
RCAN1 is named in the same sentence as 135 diseases in open-access papers, as found by Europe PMC text mining. Sharing a sentence is not in itself a finding about the gene and the disease. The quoted sentences say what the papers report.
Down syndrome (60 papers, 2009 to 2025). "One example is the Regulator of Calcineurin 1 (RCAN1), which was linked to CHDs associated with Down syndrome." (PMID 36675070, 2023). "The RCAN1 gene is also located on the human chromosome 21, is highly expressed in the human brain and is considered to be associated with Down syndrome traits." (PMID 23825664, 2013). "Secondly, individuals with Down syndrome have a low risk for solid tumors, which has been suggested to be related to the negative regulation of angiogenesis by RCAN1." (PMID 23825664, 2013). "Efforts to identify genes on human chromosome 21 with the potential to cause the brain anomalies observed in Down syndrome (DS), led to the discovery of a gene, Down syndrome candidate region-1 (DSCR1) now renamed RCAN1 (Regulator of Calcineurin-1)." (PMID 21364922, 2011). "However, recent data indicate that both loss and overexpression of RCAN1 in the hippocampus can be detrimental, promoting memory deficits and pathophysiology similar to that observed in AD and Down syndrome patients." (PMID 40414897, 2025). "The regulator of calcineurin (RCAN1) has been implicated in the pathogenesis of Down syndrome (DS)." (PMID 36429004, 2022). "An exacerbated RCAN1 has been found to reduce cancer risk in Down Syndrome individuals." (PMID 25713607, 2014). "In Down Syndrome patients, even in Alzheimer disease, an increased RCAN1 gene expression may be associated with atherosclerosis, aging, stroke, diabetes." (PMID 25713607, 2014). "Down Syndrome Critical Region 1 (Dscr1 also known as Rcan1), a negative regulator of calcineurin and suppressor of angiogenesis lies in the region of human chromosome 21, which in the trisomic state is implicated as the major cause of Down’s Syndrome." (PMID 23148642, 2012). "The RCAN1 locus is at chromosome 21q22.12 in humans, close to the Down Syndrome Critical region, and has been implicated in the pathophysiology of Down Syndrome and Alzheimer's disease, has been shown to regulate vascular function and has been proposed to play an important role in the brain." (PMID 19725972, 2009). "Considering that RCAN1 overexpression is a hallmark of Down syndrome, it can be hypothesized that this event also contributes to the pathogenesis of AD-like neuropathology typically observed in Down syndrome patients after their middle age." (PMID 27597899, 2016). "Down syndrome critical region 1 (DSCR1, also known as regulator of calcineurin 1, RCAN1) is upregulated in the tissues of patients with Down syndrome, especially in the brain, mechanistically linking to learning and memory impairments." (PMID 40612953, 2025). "It has been revealed that RCAN1 plays a critical upstream role in epigenetic regulation of adult neurogenesis, hence important in the pathogenesis of Down syndrome." (PMID 39290359, 2024). "Regulator of calcineurin 1 (RCAN1) is overexpressed in Down syndrome (DS), but RCAN1 levels are also increased in Alzheimer’s disease (AD) and normal aging." (PMID 35610565, 2022). "The RCAN1BAC−Tg mouse line, where RCAN1 expression is moderately higher than expression of the native RCAN1 gene, was generated to explore the biochemistry of RCAN1 and its role in Down syndrome." (PMID 35717152, 2022). "As it is located on human chromosome 21, RCAN1 has been postulated to contribute to mental retardation in Down syndrome." (PMID 35831802, 2022). "The study presented here used an immortalized enamel cell line to overexpress RCAN1 to mimic the possible effects that would be expected in enamel cells of Down syndrome patients." (PMID 36429004, 2022). "RCAN1 plays an important role in the pathogenesis of Down syndrome, as well as AD, through inhibition of the NFAT and NF-κB signaling pathways and thereby induces neuronal apoptosis." (PMID 34069857, 2021). "This is in contrast to Down syndrome and Alzheimer’s disease, where overexpression of RCAN1 has been reported." (PMID 32050523, 2020).
Down syndrome (continued). "There was also a conducted research about the rate of fibroblast proliferation and its major regulators, such as Rcan1 or telomere length, for assessing the oxidative balance of these cells in fetuses with Down syndrome." (PMID 33014274, 2020). "rcan-1 encodes an ortholog to human RCAN1/DSCR1 calcipressin gene, which has been implicated as a causal gene for Down syndrome." (PMID 32092052, 2020). "RCAN1, initially referred to DSCR1, MCIP1, or Adapt78, was first identified as a Down syndrome critical region gene on human chromosome 21q22." (PMID 32589657, 2020). "The results obtained showed reduced levels of antioxidants that cooccurred with increased Rcan1 levels and telomere shortening, responsible for increased oxidative stress and cell cycle disorders of fibroblasts of fetal's with Down syndrome." (PMID 33014274, 2020). "Although we did not identify any de novo SNVs or small indels on chromosome III in the RILhf strain, we did identify a large increase in coverage (2x – 8x) in the rcan-1 gene, which is an ortholog of human Down Syndrome gene RCAN1." (PMID 32092052, 2020). "In humans, RCAN1 plays an important role in human health; it has been proposed to be a key contributor to Down Syndrome phenotypes in patients with trisomy 21 and chronic overexpression of RCAN1 in mice results in phenotypes related to Alzheimer’s disease." (PMID 32092052, 2020). "None of the enriched sets of pathways and functions associated with SCN1A was associated with the Down syndrome genes (DYRK1A, PSMG1, RCAN1, DSCR3, DSCR4) or with TSC2." (PMID 29518120, 2018). "Nevertheless, both mouse models carry most of the gene complement of the Down syndrome critical region, including RCAN1, APP, SOD1 and DYRK1A." (PMID 30034324, 2018). "Intriguingly, similar to Down syndrome individuals, RCAN1 mRNA levels are elevated two- to threefold in the brains of Alzheimer's disease patients." (PMID 26658127, 2015). "Here, the authors report reduced sympathetic neural innervation in human Down syndrome tissues and a mouse model, and propose a role for RCAN1 trisomy in disrupted NGF receptor trafficking and neurotrophic support." (PMID 26658127, 2015). "RCAN1 gene is located in the minimal candidate region for the Down syndrome phenotype, and is overexpressed in the brain of Down syndrome fetuses." (PMID 25767303, 2014). "Regulator of calcineurin 1 (RCAN1; also referred as DSCR1 or MCIP1) is located in close proximity to a Down syndrome critical region of human chromosome 21." (PMID 25144594, 2014). "Several studies showed that RCAN1 gene expression is elevated in brains of Alzheimer patients and Down Syndrome fetuses." (PMID 25713607, 2014). "It is noteworthy that this NAT has been described as capable of regulating RCAN1 gene expression and patented as a putative agent for the treatment of Down’s syndrome (patent WO/2010/151674 A2)." (PMID 24465593, 2014). "We show here that the overexpression of the Down syndrome-related genes Dyrk1A and Rcan1 reduce the effect of NGF on NFAT promoter activity and the upregulation of PAI-1 in PC12 cells." (PMID 23825664, 2013). "Regulator of calcineurin 1 (RCAN1/DSCR1P1) is located near the Down syndrome critical region on the distal part of chromosome 21, and its gene product is an endogenous inhibitor of calcineurin signaling." (PMID 23118980, 2012). "Rcan1 is highly expressed in brain, and elevated expression of Rcan1 transcript and protein in the brains of Down syndrome fetuses and Alzheimer patients has been described, as well as reduced Rcan1-1 expression in Huntington disease." (PMID 22397398, 2012). "In mammals, the homolog of S. cerevisiae Rcn1 is named DSCR1/Rcan1/calcipressin and is overexpressed in the brain of patients with Down’s syndrome." (PMID 22690377, 2012). "DSCR1/ RCAN1 is a chromosome 21 gene found to be overexpressed in the brains of Down syndrome (DS) and postulated as a good candidate to contribute to mental disability." (PMID 21364922, 2011).
Down syndrome (continued). "Chromatin-immunoprecipitation and sequencing analysis confirmed that Olig2 directly targets the promoter and/or enhancer regions of Nfatc4, Dscr1/Rcan1 and Dyrk1a, the critical neurogenic genes that contribute to Down syndrome phenotypes and inhibit their expression." (PMID 38474215, 2024). "In particular, the g.482G>T variant was found to enhance RCAN1 promoter activity leading to overexpression of the RCAN1.4 isoform, potentially causing CHDs in the absence of Down syndrome." (PMID 36675070, 2023). "As a consequence, RCAN1 impacts cellular signaling through calcineurin-dependent transcript factors, such as NFAT (nuclear factor of activated T cells); plays a role in mitochondrial function; and has been implicated in several Down syndrome (DS) pathologies." (PMID 36429004, 2022). "The RCAN1 gene is located on human chromosome 21 (HSA21), trisomy of which causes Down syndrome." (PMID 36429004, 2022). "Knowledge of the consequences of human Rcan1 overexpression is limited to evidence of genetic dysfunctions secondary to trisomy of chromosome 21 in patients with Down syndrome, who present defects of the immune system, though the prevalence of allergy is not high in these individuals." (PMID 29104573, 2017). "A high oxidative stress activates the RCAN1-calcineurin-SOD pathway by an unknown mechanism and paradoxically Down Syndrome subjects could have less cardiovascular risk factors relative to cytogenetically normal individuals." (PMID 25713607, 2014). "Dysregulation of endocytosis in Down syndrome has been linked to an increased dose of several endosomal pathway-related genes that map to chromosome 21, such as amyloid precursor protein (APP), synaptojanin-1 (SYNJ1), intersectin-1 (ITSN1), and regulator of calcineurin 1 (RCAN1)." (PMID 38540156, 2024). "A previous study demonstrated that mutated JAK2 (Janus kinase 2), not dysfunctional RCAN1, may be a common molecular event in leukemia associated with Down syndrome." (PMID 35717152, 2022). "Thus, we hypothesized that dysfunctional calcineurin signalling through increased RCAN1 dosage is a potential link between deficits in TrkA trafficking and decreased neurotrophic support in Down syndrome." (PMID 26658127, 2015). "Nevertheless, given that the blood PAI-1 levels in Down syndrome individuals are lower than in controls we hypothesize that the attenuation of the NGF-induced PAI-1 by overexpression of DYRK1A and RCAN1 due to trisomy 21 may be relevant to several Down syndrome features." (PMID 23825664, 2013). "The negative effect of DYRK1A and RCAN1 on PAI-1 expression could contribute to the reduced cancer risk in Down syndrome." (PMID 23825664, 2013). "The overexpression of HSA21 genes like DSCAM, RCAN1, and DYRK1A in Down syndrome disrupts calcium homeostasis, primarily by suppressing the calcineurin pathway." (PMID 40964031, 2025). "The regulator of calcineurin 1 (RCAN1) is expressed in neurons and overexpressed in the brains of individuals with both Down syndrome and Alzheimer’s disease (AD)." (PMID 34796296, 2021). "The gene Regulator of calcineurin 1 (RCAN1; also called as DSCR1, Adapt78, MCIP1 or calcipressin 1) is located on chromosome 21, near the Down syndrome critical region." (PMID 23118980, 2012). "Neurogenesis-related genes such as DYRK1A and RCAN1, craniofacial defect-related genes such as DYRK1A, ETS2, and RCAN1, and tumor suppressor-related genes such as DYRK1A, ETS2, and RCAN1 were also reported in Down syndrome." (PMID 34433490, 2021). "RCAN1, a negative feedback regulator of NFAT activation, was implicated in rendering resistance to the development of various cancers in Down’s syndrome patients." (PMID 25811856, 2015). "We show that excess regulator of calcineurin 1 (RCAN1), an endogenous inhibitor of the calcineurin phosphatase that is triplicated in Down syndrome, impairs neurotrophic support of sympathetic neurons by inhibiting endocytosis of the nerve growth factor (NGF) receptor, TrkA." (PMID 26658127, 2015).
Down syndrome (continued). "In this study the humoral and cellular aspects of immune response were evaluated, as well as the quantitative expression of the RCAN1 gene in a sample population of adults with DS and in an ID group without Down syndrome with a similar environmental condition." (PMID 21496308, 2011). "In Down syndrome, the overexpression of genes located on chromosome 21—particularly those involved in angiogenesis inhibition, such as COL4A3, endostatin (COL18A1), and RCAN1—is known to contribute to vascular immaturity, pulmonary hypoplasia, and increased risk for pulmonary hypertension." (PMID 41462807, 2025). "Taken together, DYRK1A and RCAN1 can act synergistically to block NFAT-dependent transcription, suggesting that the reduced NFAT activity resulting from the 1.5-fold overexpression of DYRK1A and RCAN1 could be the basis of many features of Down syndrome." (PMID 23825664, 2013). "The authors concluded that the negative effect of DYRK1A and RCAN1 overexpression on NGF signal transduction in neural cells may contribute to the altered neurodevelopment and brain function in Down syndrome." (PMID 29342922, 2018). "The negative effect of DYRK1A and RCAN1 overexpression on NGF signal transduction in neural cells may contribute to the altered neurodevelopment and brain function in Down syndrome." (PMID 23825664, 2013).
Alzheimer disease (29 papers, 2011 to 2023). A progressive, neurodegenerative disease characterized by loss of function and death of nerve cells in several areas of the brain leading to loss of cognitive function such as memory and language. "Alzheimer’s disease is also associated with CMA since the beta-amyloid peptide (Aβ), the microtubule-associated protein Tau or the Regulator of calcineurin 1 (RCAN1) are involved in Alzheimer’s disease and are dysregulated when CMA is altered." (PMID 32792938, 2020). "The association between CMA and Alzheimer's Disease (AD) can be described by the degradation of the RCAN1 protein (Regulator of calcineurin 1) through this pathway." (PMID 30766511, 2018). "In contrast with high levels of RCAN1 expression in Alzheimer disease, depressed levels of RCAN1-1L are a hallmark of Huntington’s disease, a disease characterized by neuronal death caused by a mutant huntingtin protein." (PMID 29270905, 2017). "RCAN1, a regulator of calcineurin, has also been linked to both DS and Alzheimer disease as well as another neurological disorders." (PMID 29270905, 2017). "RCAN1-1L is transiently elevated to defend against acute stress including oxidative stress; however, long-term elevation of RCAN1-1L is linked to DS and Alzheimer disease." (PMID 29270905, 2017). "Memantine has been approved for use in moderate to severe Alzheimer’s Disease (AD) and interest in its possible use in DS originally stemmed from functional information on one Hsa21 encoded protein, regulator of calcineurin 1, RCAN1." (PMID 25793384, 2015). "Mouse models of RCAN1 overexpression have shown a role of RCAN1 regulating exocytosis in chromaffin cells and in mutant huntingtin phosphorilation, suggesting a role of RCAN1 in the Alzheimer's disease neuropathology associated to DS and in Huntington's disease." (PMID 21364922, 2011). "It has been reported that RCAN1 is significantly upregulated in neuronal cells of patients with DS and Alzheimer’s disease, and β cells in type 2 diabetes, accompanied by disruption of mitochondrial homeostasis." (PMID 36071051, 2022). "Numerous studies have shown that RCAN1 is involved in pathophysiological processes such as Alzheimer’s disease, myocardial ischemia-reperfusion injury, and diabetes." (PMID 36071051, 2022). "RCAN1 overexpression also promotes age-dependent mitochondrial dysregulation and progressive neurodegeneration in Alzheimer’s disease." (PMID 31894838, 2020). "Furthermore, CMA is also able to degrade the regulator of calcineurin 1 (RCAN1), a protein linked to neuronal death and frequently highly expressed in the brains of patients with Alzheimer’s disease." (PMID 32971884, 2020). "In patients with Alzheimer disease, RCAN1-1L is expressed twice as much relative to non-Alzheimer disease controls suggesting that RCAN1-1L may have a role in Alzheimer disease." (PMID 29270905, 2017). "Interestingly, DYRK1A and RCAN1 contribute to the learning and memory deficit, altered synaptic plasticity, impaired cell cycle regulation, and Alzheimer Disease-like neuropathology in DS." (PMID 25767303, 2014). "Among the differentially expressed proteins, there were proteins involved either in the neurogenic process (e.g. GDF11) or in Alzheimer’s disease (e.g. LRRK2, RCAN1, NTRK2), or in both neurogenesis and Alzheimer’s disease (e.g. CREBBP, SFRP1, IL1RAP)." (PMID 36703180, 2023). "Thus genes such as RUNX1 (which may contribute to childhood leukaemia in people with DS), APP (a key Alzheimer disease gene) and SYNJ1, RCAN1 and ITSN1, which have been linked to endosomal/synaptic abnormalities are unlikely to contribute to the phenotype of this mouse model of DS." (PMID 23596509, 2013). "We also examined RCAN1 and ITSN1-S and -L in post-mortem brain tissue in a separate cohort of patients with AD or other types of dementia including Dementia with Lewy Bodies (DLB) and non-Alzheimer’s disease dementia." (PMID 31263630, 2019).
Alzheimer disease (continued). "In addition, RCAN1-1S over-expression in the hippocampal neuronal cell line HT22 cell line resulted in hyperphosphorylation of tau, which positions Rcan1 as an important candidate for further investigation in DS-related Alzheimer’s disease features." (PMID 25052193, 2014).